SHMT2 (serine hydroxymethyltransferase 2)
Description:
Catalyzes the cleavage of serine to glycine accompanied with the production of 5,10-methylenetetrahydrofolate, an essential intermediate for purine biosynthesis. Serine provides the major source of folate one-carbon in cells by catalyzing the transfer of one carbon from serine to tetrahydrofolate. Contributes to the de novo mitochondrial thymidylate biosynthesis pathway via its role in glycine and tetrahydrofolate metabolism: thymidylate biosynthesis is required to prevent uracil accumulation in mtDNA. Also required for mitochondrial translation by producing 5,10-methylenetetrahydrofolate; 5,10-methylenetetrahydrofolate providing methyl donors to produce the taurinomethyluridine base at the wobble position of some mitochondrial tRNAs. Associates with mitochondrial DNA. In addition to its role in mitochondria, also plays a role in the deubiquitination of target proteins as component of the BRISC complex: required for IFNAR1 deubiquitination by the BRISC complex.
Synonyms: SHMT; mSHMT; GLYA; HEL-S-51e; NEDCASB
Tractability: Small molecule: a structure with a bound ligand is known; a high-quality ligand is known. PROTAC: ubiquitination databases record sites on it; its protein half-life has been measured; a small molecule that binds it is known.
Target class: Enzyme; Transferase
Gene: Protein-coding gene on chromosome 12 (57,226,554 to 57,234,935, forward strand). Ensembl gene ENSG00000182199.
Subcellular location: Mitochondrion; Mitochondrion matrix, mitochondrion nucleoid; Mitochondrion inner membrane; Cytoplasm; Nucleus
Subcellular location (Human Protein Atlas): Mitochondria; Microtubules
Pathways (Reactome):
Metabolism: Metabolism of folate and pterines
Metabolism of proteins: Mitochondrial protein degradation
Signal Transduction: RHOG GTPase cycle
Gene Ontology:
Molecular function: chromatin binding; glycine hydroxymethyltransferase activity; hydroxytrimethyllysine aldolase activity; identical protein binding; protein binding; pyridoxal phosphate binding; amino acid binding; L-allo-threonine aldolase activity
Biological process: glycine metabolic process; L-serine metabolic process; one-carbon metabolic process; protein homotetramerization; protein K63-linked deubiquitination; protein tetramerization; regulation of aerobic respiration; regulation of mitochondrial translation; regulation of oxidative phosphorylation; response to type I interferon; tetrahydrofolate metabolic process; formate biosynthetic process; glycine biosynthetic process; positive regulation of cell population proliferation; tetrahydrofolate interconversion
Cellular component: BRISC complex; cytoplasm; extracellular exosome; mitochondrial inner membrane; mitochondrial matrix; mitochondrial nucleoid; mitochondrion; nucleus
Genetic constraint (gnomAD): Loss-of-function variants: 38 observed, 62.77 expected, observed/expected ratio (o/e) 0.61, 90% interval 0.47 to 0.79. The upper end of that interval is the gene's LOEUF score, 0.79, which puts it in group 3 of 6, group 1 being the genes least tolerant of losing a copy. Missense variants: 533 observed, 685.1 expected, observed/expected ratio (o/e) 0.78, 90% interval 0.72 to 0.84. Synonymous variants: 254 observed, 269.87 expected, observed/expected ratio (o/e) 0.94, 90% interval 0.85 to 1.04.
Gene-disease validity (ClinGen):
ClinGen rates the evidence that SHMT2 causes each of these diseases.
neurodevelopmental disorder with cardiomyopathy, spasticity, and brain abnormalities (autosomal recessive): Limited.
Homologues: Orthologues: chimpanzee SHMT2 (99% identical), macaque SHMT2 (99% identical), rabbit SHMT2 (95% identical), dog SHMT2 (95% identical), guinea pig SHMT2 (95% identical), mouse Shmt2 (94% identical), rat Shmt2 (94% identical), pig SHMT2 (94% identical), tropical clawed frog shmt2 (79% identical), zebrafish shmt2 (76% identical). Paralogues in human: SHMT1 (61% identical).
Diseases named in the same sentence as SHMT2 in open-access papers:
SHMT2 is named in the same sentence as 144 diseases in open-access papers, as found by Europe PMC text mining. Sharing a sentence is not in itself a finding about the gene and the disease. The quoted sentences say what the papers report.
breast carcinoma (43 papers, 2013 to 2025). "The expression levels of serine hydroxymethyltransferase 2 (SHMT2) are positively associated with the grade of breast cancer." (PMID 40723225, 2025). "The association between SHMT2 overexpression and poor prognosis underscores its potential as a prognostic biomarker in breast cancer management." (PMID 41154605, 2025). "In both glioma and breast cancer, SHMT2 is associated with tumor aggressiveness and is an independent predictor of prognosis." (PMID 35018218, 2022). "Increased SHMT2 positively correlates with the breast cancer grade and is associated with worse relapse-free survival (RFS), distant metastases, and overall survival (OS) in breast cancer patients (N = 801)." (PMID 30857125, 2019). "SHMT2 has been implicated as an essential factor in serine and glycine metabolism in several cancer cell types, including breast cancer." (PMID 29020998, 2017). "Elevated SHMT2 expression has been linked to poorer prognosis in breast cancer patients." (PMID 41154605, 2025). "Notably, recent studies have linked SHMT2 overexpression with resistance to clinical therapy in breast cancer." (PMID 34476002, 2021). "Similarly, another study showed that SHMT2 protein expression was detected in 128 breast cancer cases and associated with tumour aggressiveness (TNM staging and Elson grade) in a dose-dependent manner." (PMID 34476002, 2021). "Considering the metabolic heterogeneity of breast cancer, SHMT2 and ASCT2 might be useful as potential markers in risk stratification and targets for drug development." (PMID 29020998, 2017). "Moreover, SHMT2 has been found to be associated with a poor prognosis in hepatocellular carcinoma, intrahepatic cholangiocarcinoma, breast cancer and gastrointestinal tumors." (PMID 34149818, 2021). "Another study reported that levels of SHMT2, a mitochondrial enzyme producing glycine from serine, correlated with enhanced proliferation of cancer cells, while the increased expression of this enzyme was associated with greater mortality in breast cancer patients." (PMID 23936142, 2013). "SHMT2 promotes breast cancer cell proliferation through the activation of vascular endothelial growth factor (VEGF) and mitogen-activated protein kinase (MAPK) signaling pathways." (PMID 41154605, 2025). "Enhanced expression of mitochondrial folate cycle enzymes such as SHMT2, MTHFD2, and MTHFD1L was also detected in cancer cell lines using metabolic profiling, and this was associated with higher mortality in breast cancer patients." (PMID 38698089, 2024). "SHMT2 is a key enzyme in serine metabolism, and is highly expressed in a variety of tumors, including breast cancer, lung cancer, B-cell lymphoma and gastric cancer." (PMID 38272883, 2024). "SHMT2 is also highly expressed in breast cancer and can be used as a prognostic indicator to assist in breast cancer treatment and diagnosis." (PMID 38577602, 2024). "A study showed that SHMT2 also played a role in the development and metastasis of breast cancer, possibly through circRNA mediated miR-149-5P overexpression of SHMT2." (PMID 38188143, 2024). "Aggressive breast cancer cell lines also show upregulation of mitochondrial serine and 1C metabolism and in patients, expression of SHMT2 is correlated with poor survival." (PMID 38698089, 2024). "SHMT2 overexpression was reported to be related to breast cancer tumor aggressiveness in a dose-dependent manner." (PMID 38136676, 2023). "Increased SHMT2 protein expression has been reported in several cancer types, including lymphoma, glioma, cholangiocarcinoma, and breast cancer." (PMID 37749499, 2023). "SHMT2 has shown prognostic and therapeutic value for many cancers, such as hepatic carcinoma, breast cancer, glioma, and thyroid cancer." (PMID 35333683, 2022). "Another study indicated that higher SHTM2 expression was also observed in lapatinib-resistant breast cancer cells, and activation of SHMT2 enhanced breast cancer cell resistance to lapatinib." (PMID 36213384, 2022).
breast carcinoma (continued). "Given the role of SHMT2 as an independent predictor of prognosis in breast cancer and glioma, we sought to determine the potential relationship between SHMT2 gene expression and overall survival in NB patients." (PMID 35018218, 2022). "SHMT2 has been shown to be upregulated in hypoxia and plays a key role in proliferation in areas of ischemia in other cancers, such as gliomas and breast cancer." (PMID 35018218, 2022). "Higher SHTM2 expression was also observed in lapatinib-resistant breast cancer cells, and activation of SHMT2 enhanced breast cancer cell resistance to lapatinib." (PMID 36213384, 2022). "Upregulation of SHMT2 is found in many types of cancers, including lymphoma, glioma, cholangiocarcinoma and breast cancer." (PMID 35018218, 2022). "SHMT2 catalyzes the first step of one-carbon metabolism, and the high expression of SHMT2 was significantly correlated with poor survival in breast cancer." (PMID 34953500, 2021). "SHMT2 overexpression is observed in various cancers, including breast cancer, melanoma, lung cancer, ovarian cancer, and prostate cancer, and is associated with tumorigenesis and progression 6-8." (PMID 33456583, 2021). "Another study in breast cancer demonstrated that SHMT2 acts as the first rate-limiting enzyme in one-carbon pathway, promoting rapid cell growth and increasing the potential for metastasis." (PMID 33863325, 2021). "Hypoxia-inducible factors (HIF) has reported to regulate expression of genes encoding PHGDH and five downstream enzymes including MTHFD2 and SHMT2 in the serine synthesis pathway and mitochondrial one-carbon cycle in breast cancer stem cells." (PMID 33468252, 2021). "In breast cancer, SHMT2 upregulation leads to an increased concentration of nicotinamide adenine dinucleotide phosphate (NADPH) and improves redox balance, which in turn facilitates cancer cell growth under hypoxic conditions." (PMID 33456583, 2021). "Several studies have validated that SHMT2 expression is elevated in breast cancer, intrahepatic cholangiocarcinoma and gastric cancer, and high levels of SHMT2 are associated with poor prognosis of patients." (PMID 33863325, 2021). "Consistently, there was a significant correlation between the expression level of SHMT2 and breast cancer grade." (PMID 34476002, 2021). "In cases involving stage IIb breast cancer, chemotherapy significantly extended survival time among patients with higher SHMT2 expression." (PMID 34476002, 2021). "Similar results were also observed in the breast cancer cell MDA-MB-231 with genetic inactivation of SHMT2." (PMID 32974014, 2020). "In contrast, OSCC patients with a lower SHMT2 expression possess higher overall survival rates and better prognoses, similar with the results in breast cancer." (PMID 33163414, 2020). "More importantly, SHTM2 expression was significantly down-regulated by lapatinib treatment; a higher SHTM2 expression was also observed in lapatinib-resistant breast cancer cells, indicating the effect of SHMT2 on breast cancer resistance to lapatinib." (PMID 31894856, 2020). "SHMT2 inhibitor has emerged as an effective adjuvant agent for breast cancer treatment using lapatinib, which needs further in vivo and clinical investigation." (PMID 31894856, 2020). "The clinical data analyses also identify SHMT2 expression as a dangerous factor for patients with breast carcinoma, of which the expression level is positively correlated with breast cancer grade." (PMID 31894856, 2020). "To test the metabolic switch beyond the HAP1 background, we generated a panel of SHMT2 deficient cell lines for the colorectal cancer cell line HCT116 and breast cancer cell lines MDA-MB-231, SKB3, T47D and MDA-MB-468." (PMID 32366892, 2020). "In summary, ERRα exerts its effects on the resistance of breast cancer to lapatinib via regulating SHMT2." (PMID 31894856, 2020). "High SHMT2 expression is considerably related to lower overall survival in patients with breast carcinoma." (PMID 31894856, 2020).
breast carcinoma (continued). "In summary, SHMT2 and ASCT2 protein expression were identified as novel potential prognostic biomarkers for patients with breast cancer, as their high protein expression is associated with poor outcome." (PMID 29020998, 2017). "Our analysis highlighted the relevance of PHGDH and SHMT2 expression as prognostic factor for breast cancer, revealing a substantial ability of these enzymes to predict patient survival outcome." (PMID 25436979, 2014). "Notably, SHMT2’s prognostic value appears more significant in ER- breast cancer cases, indicating its potential as a biomarker for this subgroup." (PMID 41154605, 2025). "In breast cancer, previous IHC studies demonstrated that SHMT2 protein was significantly overexpressed in breast cancer tissues compared to noncancerous tissues, which correlated with increased tumour aggressiveness, including advanced TNM staging and higher Elston grade." (PMID 41154605, 2025). "Likewise, serine hydroxymethyltransferase 2 (SHMT2) activated in lapatinib-resistant breast cancer promotes the synthesis of glycine and increases the synthesis of GSH." (PMID 38982494, 2024). "In addition, the circRNA circ_0072995 was demonstrated to promote a malignant phenotype and anaerobic glycolysis by competitively binding miR-149-5p to upregulate its downstream gene SHMT2 in breast cancer." (PMID 37147729, 2023). "miR-149-5p can directly target SHMT2 mRNA in breast cancer cells." (PMID 37204526, 2023). "Interestingly, a few other cancer types, such as some human breast cancers, adrenocortical carcinoma and kidney chromophobe cell carcinoma, also exhibit an increased SHMT2 expression in metastatic tumor tissue during cancer progression." (PMID 39872059, 2023). "Emerging studies have demonstrated the pivotal roles of SHMT2 protein in breast cancer progression." (PMID 34476002, 2021). "While the exact role of serine methyltransferases in ER+ breast cancer remains unknown, a number of recent studies have begun to demonstrate a significant role for one carbon metabolism and SHMT2, which is transcriptionally activated by ERRα." (PMID 34638293, 2021). "Moreover, SHMT2 has been reported to be up-regulated in a variety of cancers such as breast cancer, hepatocellular carcinoma, and lung cancer, and elevated expression of SHMT2 is significantly associated with poor prognosis of patients." (PMID 33863325, 2021). "In vivo, SHMT2 inhibition also reduced breast cancer growth of primary and metastatic sites." (PMID 33863325, 2021). "In addition, ERRα can activate SHMT2 transcription by targeting its promoter region to enhance breast cancer resistance to lapatinib." (PMID 34149818, 2021). "Similarly, a series of studies have reported that SHMT2 expression is increased in a subset of human cancers including colon cancer, breast cancer, lung cancer, ovarian cancer and prostate cancer." (PMID 34476002, 2021). "Collectively, these results indicated that SHMT2 may be a valuable prognostic biomarker in breast cancer." (PMID 34476002, 2021). "Based on these analyses, we hypothesize that ERRα might modulate the resistance of breast cancer to lapatinib via regulating SHMT2." (PMID 31894856, 2020). "In conclusion, ERRα knockdown suppresses the detoxification and the mitochondrial metabolic adaption in breast cancer resistant to lapatinib; ERRα activates SHMT2 transcription via targeting its promoter region, therefore enhancing breast cancer resistance to lapatinib." (PMID 31894856, 2020). "Current studies showed that SHMT2 may be participated in several kinds of cancers, such as breast cancer, glioma, intrahepatic cholangiocarcinoma and colorectal cancer." (PMID 33066813, 2020). "The Spearman’s correlation analysis revealed that ERRα could be positively related to SHMT2 (R = 0.34, P < 0.001) based 526 cases of breast cancer patients in TCGA database." (PMID 31894856, 2020).
breast carcinoma (continued). "In addition, analyses of publicly available data sets revealed that the mRNA levels of the ISR‐related antioxidant genes, HMOX1 and SHMT2, negatively correlated with relapse‐free survival of breast cancer patients." (PMID 31211507, 2019). "Clinically breast cancer patients with high expression of SHMT2 showed poorer survival outcome." (PMID 27391339, 2016). "In addition, the human oestrogen receptor-related receptor α could indirectly activate SHMT2 expression and then increase the resistance of breast cancer to lapatinib." (PMID 38188143, 2024). "In addition, previous reports have indicated that SHMT2 expression is upregulated in various types of cancer, including hepatocellular carcinoma, intrahepatic cholangiocarcinoma, breast cancer and gastrointestinal tumors." (PMID 34149818, 2021). "Finally, we detected the dynamic effects of ERRα and SHMT2 to estimate whether ERRα modulates breast cancer cell resistance to lapatinib through SHMT2." (PMID 31894856, 2020). "ERRα was predicted to bind to the serine hydroxymethyltransferase 2 (SHMT2) transcription initiation site in the ER- and HER2-positive cell line BT-474; thus, we hypothesize that ERRα might modulate the resistance of breast cancer to lapatinib via regulating SHMT2." (PMID 31894856, 2020). "Serine hydroxymethyltransferase 2 (SHMT2), an enzyme that converts serine to glycine, is shown as a prognostic marker and therapeutic target for breast cancers." (PMID 37046596, 2023). "In fact, genomic analyses have shown that many cancers, especially breast cancer and non-small cell lung cancer (NSCLC), exhibit amplification and upregulated expression of SGOC metabolic enzymes, such as PHGDH and SHMT2." (PMID 37147729, 2023). "c-Myc also upregulates SHMT2 under hypoxia, and both the SHMT2 and PHGDH enzymes are positively correlated with each other in cancers such as breast cancer and neuroblastoma." (PMID 36613455, 2022). "Through proteomic profiling, we discovered a metabolic signature comprised of TALDO1, GPI, LDHA, SHMT2, and ADK proteins that were downregulated in Trop2-depleted breast cancer tumors." (PMID 34711841, 2021). "Qi and collaborators found that circ_0072995 promotes breast cancer cell progression by acting as a sponge for miR-149-5p, thereby upregulating serine hydroxymethyltransferase 2 (SHMT2), an oncogene in breast cancer." (PMID 34722295, 2021). "In summary, the purpose of our study was to explore a novel regulatory mechanism of ERRα serving as a transcription factor to activate the transcription of SHMT2 and to affect ER- and HER2-positive breast cancer cell resistance to lapatinib." (PMID 31894856, 2020). "Univariate and multivariate analyses supported the crucial role of SHMT2 and ASCT2 protein expression as independent prognostic factors in breast cancer." (PMID 29020998, 2017). "For instance, the molecular mechanisms and functional behavior of SHMT2 and ASCT2 in breast cancer merit further exploration." (PMID 29020998, 2017). "Although our study revealed the clinical significance of SHMT2 and ASCT2 in breast cancer, some limitations warrant further investigation." (PMID 29020998, 2017). "A comprehensive proteomic analysis employing reverse-phase protein array (RPPA) technology on 289 breast cancer samples demonstrated higher ASCT2 and SHMT2 protein expression in aggressive subtypes, including HER2-positive and TNBC, compared to luminal subtypes." (PMID 41154605, 2025). "Stratified analysis results indicated that SHMT2 was helpful in predicting outcomes, especially in oestrogen receptor (ER)-negative breast cancer patients." (PMID 34476002, 2021). "Compared to that in the matched noncancerous tissues, SHMT2 protein expression was also upregulated in clinical breast cancer tissues." (PMID 34476002, 2021). "The fact that high expression of SHMT2 in 10 out of 17 breast cancer datasets predicted negative prognosis, seems to be in accord with this presumption." (PMID 30857125, 2019).